TNF (tumor necrosis factor)
Diseases named in the same sentence as TNF in open-access papers (continued):
Sharing a sentence is not in itself a finding about the gene and the disease.
psoriasis (continued). "After eight weeks of treatment, 11 out of 12 patients showed a 20–80% improvement in the Psoriasis Area and Severity Index (PASI), which was accompanied by a decreased expression of pro-inflammatory cytokines, including IFN-γ, IL-8, IL-12, TNF-α, and IL-1β." (PMID 40731810, 2025). "Cytokines like TNF-α and IFN-γ are known to stimulate KC proliferation, induce chemokine and cytokine production, and promote psoriasis progression." (PMID 41425939, 2025). "TNF-α inhibitors are approved by the U.S. Food and Drug Administration (FDA) for the treatment of moderate to severe psoriasis, and their efficacy has also been demonstrated in psoriatic arthritis therapy." (PMID 41002407, 2025). "These cytokine cocktails include the Th2-type IL-4 and IL-13, the Th1-type interferon γ (IFN-γ) and tumor necrosis factor α (TNF-α), and the Th17-type IL-17, which have been reported to be involved in skin inflammation related to human AD or psoriasis." (PMID 39852930, 2025). "Our results show that protein levels of multiple proteins (32/71) were upregulated at baseline in the lesional skin compared to non‐lesional skin, including three key biomarkers of the psoriasis disease pathology (IL‐17A, CCL20 and TNFα)." (PMID 40970551, 2025). "Furthermore, the treatment of psoriasis with TNF-α inhibitors may also have beneficial effects on the development of atherosclerosis and components of the metabolic syndrome, such as improving endothelial function, reducing the risk of diabetes mellitus, and improving insulin sensitivity." (PMID 40584532, 2025). "The production of TNF-α and IL-17 from CD3/CD28-stimulated T cells was also significantly increased, implicating these cytokines in the pathogenesis of psoriasis." (PMID 39998065, 2025). "Immunologically, psoriasis is driven by Th1/Th17 cytokines, including Interleukin (IL)-17, IL-23, Interferon-γ (IFN-γ), and Tumor Necrosis Factor-α (TNF-α)." (PMID 40506953, 2025). "Through these receptors, estrogen can downregulate the production of pro-inflammatory cytokines, such as tumor necrosis factor-alpha (TNF-α), interleukin-6 (IL-6), and interferon-gamma (IFN-γ), all of which are central to the pathogenesis of psoriasis." (PMID 39860587, 2025). "Lastly, the moderate positive correlation and low R2 values observed between TNF-α and PASI scores imply limited applicability of TNF-α as a standalone biomarker and emphasizes the intricate relationship between cytokines and psoriasis." (PMID 40699767, 2025). "Established a new model of human pre-psoriatic skin forming psoriasis-like lesions in AGR129 mice, showing crucial roles of resident T cells and TNF-α." (PMID 41209017, 2025). "At present, biological agents such as tumor necrosis factor alpha (TNF-α) and interleukin-17 (IL-17A) inhibitors are widely used to treat psoriasis and have achieved good clinical efficacy." (PMID 40441209, 2025). "In response to DAMP or PAMP stimulation, keratinocytes can produce a range of proinflammatory cytokines, including IFN-β, IL-1β, IL-36, TNF, IL-6, IL-8, IL-25, and CXCL10, which help establish the inflammatory T cell phenotype characteristic of psoriasis." (PMID 39859462, 2025). "Both vitiligo and psoriasis are driven by proinflammatory cytokines, with IFN-γ and TNF-α playing central roles in vitiligo, while IL-17, IL-23, and TNF-α are key in psoriasis, exacerbating damage through ROS in both conditions." (PMID 39860439, 2025). "Elafin expression is upregulated by pro-inflammatory cytokines like interleukin-1 (IL-1) and tumor necrosis factor-α (TNF-α), particularly in conditions like psoriasis." (PMID 40650250, 2025). "In this experiment, periodontal therapy and TNF‐α inhibitor showed a synergetic effect in the treatment of comorbid experimental ligature‐induced periodontitis and IMQ‐induced psoriasis." (PMID 40277096, 2025).
psoriasis (continued). "Evidence from this preclinical model suggests that periodontal therapy and TNF‐α inhibitor exert a positive synergetic effect in the treatment of comorbid experimental ligature‐induced periodontitis and IMQ‐induced psoriasis." (PMID 40277096, 2025). "This is in agreement with several previous biomarker studies of the PDE4 inhibitor apremilast in psoriasis patients, showing a significant modulation of TH1 and TH17 cytokines involved in the pathogenesis of psoriasis (e.g., IL‐17A/F, IL‐22 and TNFα)." (PMID 40970551, 2025). "The combination of periodontal therapy and TNF‐α inhibitor showed a positive synergetic effect in the treatment of comorbid experimental ligature‐induced periodontitis and IMQ‐induced psoriasis via the reduction of systemic inflammation." (PMID 40277096, 2025). "In this cross-sectionalstudy, 60 psoriasis patients and 30 healthy controls were evaluated; PASI scores were recorded and serum TNF-α, IL-6 and IL-17levels was measured using ELISA." (PMID 41393395, 2025). "Recent studies have elucidated the central role of tumor necrosis factor-alpha (TNF-α), IL-23, and IL-17 in the pathogenesis of psoriasis." (PMID 40937256, 2025). "Tumor necrosis factor-alpha (TNF-α), among other factors, sustains epidermal inflammation, with its expression elevated in psoriasis." (PMID 40405066, 2025). "In other inflammatory conditions, including psoriasis and PsA, both the exacerbation of existing IBD and the emergence of new cases induced by TNF inhibitors have been documented." (PMID 39807347, 2025). "The most common of these reactions is paradoxical psoriasis, which has been reported in up to 5% of patients receiving tumour necrosis factor (TNF)‐α inhibitor therapy for IBD, inflammatory arthritis and psoriasis." (PMID 40944329, 2025). "Referring to the pathogenesis, sufficient evidence suggested that DM and psoriasis shared some common inflammatory pathways, including IFN-α/β-induced response, INF-γ, and TNF-α." (PMID 39859462, 2025). "To further mitigate confounding from medication use, we included the use of TNF-alpha inhibitors, ixekizumab, ustekinumab, methotrexate, JAK inhibitors, guselkumab and several other common psoriasis and PsA therapies as covariates in our PSM approach." (PMID 40520447, 2025). "DCs in the skin release proinflammatory cytokines such as tumor necrosis factor-alpha (TNF-α), interleukin 23 (IL-23), IL-6, and IL-1b as psoriasis spreads." (PMID 38712377, 2025). "Although reported results vary, it is generally assumed that serum levels of proinflammatory cytokines, such as TNF-α, IFN-γ, IL-6, IL-8, IL-12, IL-17A, IL-18 and IL-22, are elevated in patients with psoriasis and correlate with disease severity." (PMID 40584532, 2025). "Total RNA was extracted and analyzed using qRT-PCR to assess the expression levels of psoriasis-related keratinocytes marker genes (KRT6, KRT16) and CD-related inflammatory cytokines (IL6, IL8, TNF-α)." (PMID 40406126, 2025). "Only a small percentage of psoriasis patients with vitiligo and alopecia were prescribed JAK inhibitors and a small percentage of patients with lichen sclerosus were given TNF-α inhibitors." (PMID 38957840, 2024). "Wang and colleagues reported higher lncRNA-XIST levels in patients with psoriasis compared to healthy controls and a positive correlation between lncRNA-XIST levels and the PASI score, as well as TNF-α, IL-17, and IL-22 levels." (PMID 38927529, 2024). "However, we also note that some tumor necrosis factor inhibitors may induce the onset of vitiligo, a phenomenon observed in patients with various other conditions, such as hidradenitis suppurativa, ankylosing spondylitis, Crohn’s disease, and psoriasis." (PMID 38660673, 2024).
psoriasis (continued). "However, from an immunological point of view, Psoriasis is predominantly driven by the activation of dendritic cells, T cells, and the subsequent production of pro-inflammatory cytokines, notably tumor necrosis factor-alpha (TNF-α), interleukin-17 (IL-17), and interleukin-23 (IL-23)." (PMID 39337081, 2024). "Therefore, psoriasis monoclonal antibody therapy, whether directed against TNF-alpha or IL-17, is directed against the inhibition of the Th1 pathway and will increase the response of the Th2 pathway, which results in the development of Th2-type disease, such as eczematous damage." (PMID 39777333, 2024). "The role of HSP72 in psoriasis needs more elucidation as, in one study where systemic inflammation was induced by LPS, HSP72 induced by thermal pre-treatment inhibited IL-6 and TNF-α." (PMID 38666958, 2024). "In an IMQ-induced mouse model and TNF-α/IFN-γ-activated keratinocytes, CD significantly reduced key psoriatic indicators such as skin thickness, Psoriasis Area Severity Index score, and neutrophil infiltration." (PMID 38892253, 2024). "These are present in the lesional skin of psoriasis patients; they exhibit reduced degranulation and produce lower levels of the pro-inflammatory cytokines IFN-γ and TNF-α." (PMID 38793117, 2024). "Since its first approval over 25 years back, TNF inhibition has remained one of the most widely used and successful anti-inflammatory therapeutics to control RA, IBD, and psoriasis." (PMID 39297883, 2024). "In a study, Dios inhibited cell viability and promoted apoptosis of TNF-α-induced HaCaT cells by inactivating the TLR4/NF-κB pathway, which confirmed its anti-proliferative and pro-apoptotic effects in psoriasis." (PMID 38611801, 2024). "There was highly statistically significant variance between psoriasis patients and controls as regards serum CRP and TNFα levels (P < 0.00001)." (PMID 38965465, 2024). "It inhibits TNF-α expression in the skin of psoriasis patients, thereby contributing to the therapeutic effects of IFC in psoriasis treatment." (PMID 39684717, 2024). "TNF-α suppresses IFN-α secretion, induces DC maturation, and synergizes with IL-17A to regulate psoriasis-related cytokine and keratinocyte genes." (PMID 38892253, 2024). "In a mouse model of skin inflammation induced by imiquimod, the anti-psoriasis effect of tea extract was evaluated by measuring its inhibition of several pro-inflammatory cytokines such as IL-1, IL-6, IL-22, FN, IFN-γ, and TNF-α." (PMID 38542915, 2024). "Serum levels of several proinflammatory cytokines, including TNF-α,IFN-γ,IL-6,IL-8,IL-12,IL-17A and IL-18 were elevated in individuals diagnosed with psoriasis compared to healthy controls, suggesting that psoriasis develops systemically." (PMID 38504983, 2024). "We found GPR15LG knockdown down-regulated the expressions of IL-1α, TNF-α, IL-1β and S100A7 in M5-treated HaCaT cells, suggesting a pivotal role of GPR15LG in keratinocyte-mediated inflammation in psoriasis." (PMID 38393364, 2024). "Pro-inflammatory cytokines, such as tumor necrosis factor (TNF), are involved in the pathogenesis of both psoriasis and depression." (PMID 38892934, 2024). "In this study, TAN significantly inhibited the levels of iNOS, TNFα, IL-6, IL-10, IL-20, MIF, and MCP-1 in psoriasis mice, which had a wide range of inflammatory inhibitory effects." (PMID 38832986, 2024). "In particular, several biologics have been approved during the last five years, targeting tumor necrosis factor-alpha (TNF-α) or interleukin (IL)-23, IL-12/23, or IL-17, which have been established as the pivotal cytokines in the pathogenesis of psoriasis." (PMID 38256629, 2024). "Studies have reported that methylfulvestrine improves psoriasis symptoms by inhibiting the production and release of S100A7, which is a key factor in the production of IL-6, IL-8, and TNF-α in keratinocytes." (PMID 38607144, 2024).
psoriasis (continued). "TNF-α inhibitors (e.g., infliximab and adalimumab) are FDA-approved for both psoriasis and IBD and have shown great efficacy in reducing inflammation and achieving remission​." (PMID 39463646, 2024). "TNF-α and IFN cytokines involved in psoriasis pathogenesis increase the levels of CRH as well as of adrenocorticotropic hormone (ACTH) and cortisol, which indicate the influence of inflammation on hormonal status in these patients." (PMID 38399624, 2024). "In our study, the strong increase of IL-1α, TNF-α, IL-1β and S100A7 was observed in psoriasis-like lesions." (PMID 38393364, 2024). "In vivo studies showed that isozoranthin reduced TNF-α, IL-6, IL-23, and IL-17 levels in the sera of mice, effectively alleviating IMQ-induced psoriasis in mice." (PMID 39338338, 2024). "Additionally, a comprehensive review of the literature prior to 2009 suggested that anti-TNFα treatments in psoriasis might carry an elevated risk of cancer, particularly non-melanoma skin cancers and hematologic malignancies." (PMID 38610706, 2024). "Biologic agents, particularly those targeting tumor necrosis factor-alpha (TNF-α), interleukin-17 (IL-17), and interleukin-23 (IL-23), have revolutionized the management of moderate to severe psoriasis." (PMID 39861831, 2024). "Macrophages in psoriasis are “classically activated” by IFN-γ and produce IL-23p19, IL-12/23p40, iNOS, and TNF-α." (PMID 38642273, 2024). "Proinflammatory cytokines IL-1α, TNF-α, IL-1β and S100A7 have been reported to be up-regulated in psoriatic skins and they are involved in the psoriasis pathogenesis." (PMID 38393364, 2024). "Research indicates that sustained IFN-γ release characterizes psoriasis, while the joint disruption of intestinal epithelial barriers by IFN-γ and TNF-α is crucial in UC and CD." (PMID 39544942, 2024). "Biologics that target TNF-α are often efficacious in treating both psoriasis and IBD; however, they differ greatly: etanercept, an approved treatment for psoriasis, is ineffective in treating IBD." (PMID 39463646, 2024). "Cytokine assessment involves serum TNF‐α, Ki‐67 and TGF‐β effects, comparing Sham, Psoriasis, and brilaroxazine Lipogel groups." (PMID 38363081, 2024). "IL-1β, IL-6, IL-17, TNF-α, and hs-CRP are involved in the pathogenesis of atherosclerosis, psoriasis, and RA." (PMID 38927529, 2024). "IL-17 synergizes with TNF-α to induce hyperproliferation of KCs, TH17-polarized inflammation, and upregulate psoriasis-related genes." (PMID 38642273, 2024). "A highly statistically significant difference between psoriasis patients and controls was noted as regards serum CRP and TNFα levels (P < 0.00001)." (PMID 38965465, 2024). "According to the British Association of Dermatologists Guidelines for Biologic Therapy for Psoriasis 2020, three commonly used biological agents were selected: the IL-17A inhibitor SEC, IL-12/23 inhibitor UST and TNFα inhibitor ADA." (PMID 38472183, 2024). "It has been previously demonstrated that a decrease in PPAR-alpha levels was observed in the lesional skin of patients with psoriasis and that topical PPAR-alpha agonist application decreased TNF-α and IL-1α in the skin." (PMID 38672088, 2024). "TNF is a cytokine that can bind to TNF receptor 1 (TNFR1) or TNF receptor 2 (TNFR2) and is a key factor in mediating inflammation in psoriasis." (PMID 39201000, 2024). "On the other hand, studies showed that although LP, psoriasis, and vitiligo differ in how they induce the immune system, they share many similarities in their pathogenesis with dominant Th1/IFN-γ and TNF-α cytokine profiles." (PMID 38430309, 2024).
psoriasis (continued). "Liquiritin demonstrates significant potential as a therapeutic agent for psoriasis in both in vitro (using TNF-α-stimulated HaCaT keratinocytes) and in vivo (IMQ-induced psoriasis-like mouse model) settings, where it effectively inhibits psoriasis progression." (PMID 38892253, 2024). "Whereas the other approved anti-TNF biologics are mAbs, etanercept is a fusion product of two extracellular domains of TNFR2 and the Fc region of human IgG1 Ab that is indicated for psoriasis and RA." (PMID 39297883, 2024). "Dendritic cells release TNF-α and several other cytokines such as IL-23, signaling the formation of CD4+ and CD8+ T cells at the onset of psoriasis." (PMID 39057098, 2024). "The etiology of psoriasis involves up-regulation of several pro-inflammatory cytokines, including IL-6, IL-8, IFN-γ, and TNF-α." (PMID 39777115, 2024). "TNFα, IL-17, and IL-22 stimulate ERK phosphorylation, leading to the increased expression of crucial psoriasis mediators such as IL-36α and IL-36γ." (PMID 38674130, 2024). "This is evidenced by an increased index of expansion following anti-TNF treatment for active rheumatoid arthritis or an increase in TH1/2/17 cytokines produced in IBD and psoriasis." (PMID 39591183, 2024). "It was supported by the fact that epidermal T cells in psoriasis strongly produce type 1 cytokines, including IFN-γ, IL-2, and TNF-α." (PMID 38642273, 2024). "Adalimumab, a fully human monoclonal antibody targeting tumor necrosis factor (TNF)-α, is one of the widely used TNF-α inhibitors in the treatment of CD and psoriasis." (PMID 39927272, 2024). "Therapeutic monoclonal antibodies, which target TNF-α (adalimumab, etanercept, and infliximab) or the p40 subunit of IL-12 and IL-23 (e.g., UST), have become pivotal in managing severe psoriasis and are generally well tolerated." (PMID 38256367, 2024). "α-humulene from Pini koraiensis semen was found to interact with psoriasis-related proteins such as IL1B and TNF, which play crucial roles in inducing inflammatory cytokines and amplifying immune responses." (PMID 39590306, 2024). "While Th17 cells and associated molecules, such as IL-17A, IL-17F, IL-22, and tumor necrosis factor (TNF-a), are known to be elevated in serum and psoriatic skin lesions, recent research suggests that Th17 cells are not the primary source of these pathogenic cytokines in psoriasis." (PMID 38791423, 2024). "Patients suffering from both psoriasis and CVD have increased serum levels of Th17-dependent cytokines IL-6, IL-21, IL-22 and TNF." (PMID 39200092, 2024). "The treatment of both psoriasis and IBD relies on targeting shared inflammatory pathways, especially those involving TNF-α, IL-23, and IL-17." (PMID 39463646, 2024). "Tumor necrosis factor (TNF)-α and other cytokines contribute to the creation of a pro-angiogenic microenvironment in psoriasis." (PMID 38429819, 2024). "In general, proinflammatory cytokines and factors stimulating proliferation in psoriasis are produced mainly by T cells (IL-17, IL-21, IL-22, IFN-γ), DCs (TNF-α, IL-6, IL-20, IL-23, NO), and KCs (antimicrobial peptides (AMPs), IL-20, chemokines)." (PMID 38642273, 2024). "The activation of the inflammatory pathway by tumor necrosis factor-alpha, interleukin 23, and interleukin 17 (TNF-α, IL-23, IL-17) is involved in the pathophysiology of psoriasis." (PMID 37598033, 2024). "Biological treatments for pediatric psoriasis approved by the FDA and EMA include anti-TNF agents such as etanercept and adalimumab as well as the anti-IL-12/23 ustekinumab." (PMID 38202250, 2023). "TNF-α inhibitors were found to prolong the ability of pDCs to produce type-1 IFN, which drives the differing phenotype of psoriatic lesions in paradoxical psoriasis." (PMID 37664349, 2023).